CRP (C-reactive protein)
Diseases named in the same sentence as CRP in open-access papers (continued):
Sharing a sentence is not in itself a finding about the gene and the disease.
cancer (continued). "These analyses need to be repeated using certified and distinctively separated pCRP and mCRP reagents so the true nature of “CRP” as a biological modifier in cancer can be advanced." (PMID 34552600, 2021). "Our data is the first presented in the literature to track CRP levels at different phases of treatment in any cancer." (PMID 34926085, 2021). "This analysis showed that CRP had high prediction accuracy in the discrimination of cancer and non-cancer patients with AUC values of 0.88 (sensitivity=1, specificity=0.67)." (PMID 33613752, 2021). "Studies have reported that inflammation-based markers can be used as potential prognostic factors for many cancers, including CRP, neutrophils, lymphocytes, dNLR and ALB." (PMID 34446028, 2021). "On exploratory subgroup analysis, CRP levels also positively correlated with PSA in high and intermediate-risk cancer." (PMID 34926085, 2021). "C-reactive protein (CRP) levels have been reported to be associated with weight loss, decreased QOL, and shorter survival in advanced cancer patients." (PMID 34445197, 2021). "High CRP levels at baseline were reported to be associated with poor PFS and OS in cancer patients treated with PD-1 inhibitors." (PMID 34502325, 2021). "A large proportion of studies examined CRP as a prognostic marker of cancer incidence but also of cancer survival." (PMID 32978716, 2021). "As an acute phase protein of hepatic origin, CRP reflects the process of systemic inflammation from cancer and its related complications such as cachexia, pyrexia, and fatigue." (PMID 33924623, 2021). "The data show that the preoperative plasma level of CRP was an independent significant prognostic factor for overall survival up to three years after surgery in older patients with cancer." (PMID 33920422, 2021). "Median peak CRP was 151.1 in active cancer patients and 164.0 in those with a history of cancer (p = .633)." (PMID 34409775, 2021). "In this review, we describe previous studies of how “CRP” affected various acute phase and inflammation processes of relevance in cancer disease." (PMID 34552600, 2021). "The prognostic value of both suPAR and CRP have been well-documented in different types of cancers, including NSCLC." (PMID 35155590, 2021). "p = 0.009) and CEA (1.67 vs. 1.46 ng/mL; p = 0.797) as well as CRP (16.4 vs. 1.05 mg/L; p < 0.001) were higher in the cancer group than in healthy volunteers, but only in the case of CEA was the difference not statistically significant." (PMID 34680333, 2021). "With longer follow-up, when the RT inflammation has resolved, is CRP more reflective of the cancer status?" (PMID 34926085, 2021). "Taken together, this data indicates an association between CTX and the clinical and laboratory features characterizing cancer cachexia, such as BMI, albumin, and CRP." (PMID 34182958, 2021). "The inflammatory biomarker “C-reactive protein to albumin ratio (CAR)” has been reported to significantly correlate to a variety of human cancers." (PMID 33933070, 2021). "The available literature on CRP in cancer largely focuses on pre-therapeutic levels as a prognostic marker for cancer development and treatment response." (PMID 34926085, 2021). "While median CRP was elevated in cancer cohort (p < 0.001), the median PCT levels were similar in both groups." (PMID 34786866, 2021). "One of these reviews noted that although most prevalent case-control or cross-sectional studies found higher CRP concentrations in cancer patients compared to healthy controls, prospective cohort studies provided no strong evidence for an association." (PMID 34194621, 2021). "Markers of systemic inflammation, including elevated levels of C-reactive protein (CRP) and the peripheral blood neutrophil-to-lymphocyte ratio (NLR), also have been identified as robust markers of cancer-associated inflammation." (PMID 34915912, 2021).
cancer (continued). "As with any medical condition involving a host defense response to tissue damaging pathologies, blood levels of CRP are used to monitor the presence and extent of inflammation in cancer patients." (PMID 34552600, 2021). "We have previously demonstrated that high levels of IL-6, CRP, and other pro-inflammatory cytokines in patients with advanced cancer was correlated with high levels of ROS and low levels of antioxidant enzymes." (PMID 33550983, 2021). "Among them, the abundance of Corynebacterium_1 was previously demonstrated to be correlated with serum concentrations of interleukin-6 and C-reactive protein in cancer patients." (PMID 34220499, 2021). "By reinterpreting results to include concepts of mCRP, a more consistent understanding of how “CRP” contributes to the acute phase/inflammatory response in cancer, and in any disease involving tissue damage, is advanced." (PMID 34552600, 2021). "GPS is determined by serum albumin level (cutoff value = 3.5 g/dL) and CRP level (1.0 mg/dL) and is a well-validated prognostic system in patients with advanced cancer." (PMID 34575208, 2021). "CRP is one of the most useful parameters to evaluate the inflammation status of cancer patients preoperatively or postoperatively." (PMID 34360768, 2021). "In patients with malignant tumors, CRP levels are reportedly modulated by cytokines, particularly interleukin 6, which is produced by the tumor cells themselves or by the surrounding cells." (PMID 34149913, 2021). "Together, these data indicate that “CRP” can have anti-cancer activity but that this biological activity is specific to the mCRP isoform." (PMID 34552600, 2021). "Even in a heterogeneous group of older cancer patients with different types of cancer and different disease stages, CRP is still a significant prognostic factor of overall survival." (PMID 33920422, 2021). "This involved the use of all three cancer biomarkers’ antibodies as well as the antibodies specific to interfering inflammation biomarkers, C-reactive protein (CRP) and Procalcitonin (PCT)." (PMID 34372259, 2021). "Although the underlying molecular mechanisms for this association remain unclear, a CRP increase appears also to be a sign of tumor proliferation and progressive involuntary weight and lean tissue loss, both of which are crucial elements in estimating cancer survival." (PMID 34501461, 2021). "Systemic inflammatory markers, such as CRP (C-reactive protein), was shown to be an independent predictor of poor outcome in patients suffered from various cancers." (PMID 33853556, 2021). "Few reports explored the relationship between posttreatment CRP levels and long‐term outcomes in patients with cancer." (PMID 33270989, 2021). "Higher levels of D-dimers (p = 0.001), erythrocyte sedimentation rate (p = 0.003), C-reactive protein (CRP) (p < 0.001), and lower levels of hemoglobin (p = 0.003) were associated with cancer." (PMID 33945004, 2021). "Levels of D-dimers (p = 0.001), ESR (p = 0.003), and CRP (p < 0.001) were higher in cancer patients." (PMID 33945004, 2021). "Secretion of proinflammatory adipokines such as tumour necrosis factor-α (TNF-α) and interleukin-6 (IL-6) by dysfunctional adipose tissue and an increase in inflammatory factors, such as C-reactive protein (CRP), are likely to promote cancer development." (PMID 33492550, 2021). "HR estimates were moderately attenuated especially in the last year before cancer diagnosis when adjusting for blood CRP concentrations, which have been reported as elevated during the development of cancer disease." (PMID 34036468, 2021). "Clinicaly, postoperative IL-6 and CRP are known to be useful markers of postoperative morbidity, including infection, in cancer and non-cancer patients." (PMID 34768810, 2021). "Recently, researchers have used the CRP/Alb ratio to predict the clinical prognosis of patients with cancer." (PMID 34900028, 2021).
cancer (continued). "Several other studies already identified a preoperatively elevated plasma level of CRP as a prognostic factor for survival after surgery in cancer patients for different types of cancer." (PMID 33920422, 2021). "Circulating levels of CRP have been shown to be elevated in various types of cancers from case-control or cross-sectional studies." (PMID 34194621, 2021). "Positive upper airway RV detection was associated with relapsed hematologic malignancies, higher level of C-reactive protein, and prior use of high dose steroids and anti-cancer chemotherapeutic drugs." (PMID 34905565, 2021). "This implied limitations due to the great variability of basal values induced by the disease and other treatments and the exclusion of some radiation biomarkers as C reactive protein, the free circulating DNA, proven to rise in cancer patients." (PMID 33854097, 2021). "Elevated C‐reactive protein (CRP) concentration is the most common measure of the systemic inflammatory response in cancer patients due to its sensitivity, specificity, and reproducibility in hospital laboratories." (PMID 34585050, 2021). "Inflammation-based scores consisting of CRP and ALB as the Glasgow prognostic score have been proven to be significantly associated with survival in various cancers." (PMID 33676467, 2021). "Our findings support the use of individual inflammatory marker abnormalities, in particular a raised CRP, in preference to inflammatory marker scores to triage people attending primary care with unexpected WL for cancer investigation." (PMID 33558706, 2021). "The clinical significance of lower IL-6 and CRP levels and higher ferritin levels following corticosteroid use in cancer patients also requires further inquiry." (PMID 33649382, 2021). "The Glasgow Prognostic score (GPS) is a validated tool for predicting survival for several types of cancer using a combination of CRP and albumin levels." (PMID 33920422, 2021). "CRP is another serum inflammatory marker that has been studied in numerous infections and used as a biomarker in cancer." (PMID 33924623, 2021). "Of note, the Glasgow prognostic score, an outcome prediction model for cancer patients, is based on CRP and albumin levels." (PMID 34521927, 2021). "Several biomarkers, such as C-reactive protein, platelet counts, and white blood cell counts, have also been found to represent prognostic factors in various human cancer types." (PMID 33198698, 2020). "The abundance of Corynebacterium_1 was previously demonstrated to be correlated with serum concentrations of interleukin-6 and C-reactive protein in cancer patients." (PMID 32508748, 2020). "The serum level of C-reactive protein (CRP) is the only acute phase biomarker widely used in routine clinical practice, including its uses for prognostics and therapy monitoring in cancer patients." (PMID 32707721, 2020). "Upregulated C-reactive protein (CRP) levels (CRP > 10 mg/L) have been observed in cachectic patients with cancer and it is connected with poor performance in PC patients." (PMID 32466362, 2020). "Anti-inflammatory treatment leading to the reduction of the CRP level has been proposed to represent an effective therapeutic strategy for cancer." (PMID 33023215, 2020). "In many cancer patients, as CRP increases, albumin continues to decline and albumin reflects systemic inflammation and nutritional status." (PMID 33299415, 2020). "Overview of CRP values reported in various cancers distinguishing Conventional CRP levels (≥ 10 μg/ml) from High Sensitivity (hsCRP) levels (< 10 μg/ml)." (PMID 33324413, 2020). "In particular, the GPS, an inflammation-based prognostic score that includes CRP and albumin, is one of the most useful scoring systems for prognosticating patients with various advanced cancers." (PMID 32595832, 2020). "In this study, the KD-ABC score, composed of ALB, BS, and CRP, was proposed, and it stratified the prognosis of cancer patients treated with the ketogenic diet." (PMID 32438645, 2020).
cancer (continued). "CRP is a classic acute phase reactant that is elevated in response to acute and chronic inflammation as well as cancer." (PMID 33291857, 2020). "One research group combined inflammatory biomarkers, such as C-reactive protein (CRP) and leukocyte counts, to estimate the risk of cancer development." (PMID 32722165, 2020). "Other components of CONUT score, PNI, and mGPS (i.e., CRP, lymphocytes, cholesterol) are also markers of cancer-induced inflammation or immunity to cancer." (PMID 33176752, 2020). "By considering the recent understanding that CRP exists in multiple isoforms with distinct biological activities, a unified model is advanced that describes the relevance of CRP as a mediator of host defense responses in cancer." (PMID 33324413, 2020). "Cancer cells are also able to produce many proinflammatory cytokines like IL-1 and IL-6, which stimulate the formation of CRP in the liver." (PMID 30828780, 2020). "Here we show that elevated CRP levels are common and correlate with measures of impaired cardiac function in patients who have received thoracic radiotherapy for the treatment of cancer." (PMID 32154028, 2020). "Univariable logistic regression analysis indicated that old age, comorbidity of malignant tumor, neutrophilia, lymphocytopenia, increased CRP levels, lower CD4+ T cell count, and decreased C3 levels were associated with death." (PMID 32746940, 2020). "In the present study, the apoB/apoA-I ratio was superior compared with CRP for predicting cancer mortality." (PMID 31936330, 2020). "CAR, as a star prognostic biomarker for cancer, two of whose elements, CRP and ALB, are derived from blood." (PMID 32963635, 2020). "The highest mean concentration of CRP was observed in the group of patients with malignant tumours at stage T2 and grade G3." (PMID 30828780, 2020). "C-reactive protein (CRP) has been extensively explored in advanced cancer patients as a proxy for inflammation with elevated levels associated with reduced performance status, survival and poor nutritional status." (PMID 31916005, 2020). "In cancer patients, elevated serum CRP levels are higher than those in healthy individuals and are generally associated with tumor burden, disease progression, a deteriorated physical status, and decreased survival." (PMID 33108686, 2020). "Many researches have also found that a high CRP/ALB ratio is an independent prognostic marker for cancer patients." (PMID 31998420, 2020). "The presence of C-reactive protein is proven to be an indicative biomarker of diseases such as cancer, stress, metabolic disorders, diabetes, cardiovascular diseases, and respiratory diseases." (PMID 32213807, 2020). "In this specific context, both the elevated levels of CRP and reduced levels of Alb are commonly detected in any cancer type, including the GBM, and are principally prompted through hypoxia and necrotic tumor cell-induced mediators of systemic inflammation." (PMID 32566124, 2020). "Research from the European Investigation into Cancer cohort indicates statistically significant increased risks of EC for elevated levels of prediagnostic, prospectively controlled CRP levels (OR = 1.58, 95% CI: 1.03–2.41)." (PMID 32977765, 2020). "Inflammatory nutritional factors, such as the neutrophil/lymphocyte ratio (NLR), Glasgow Prognostic Score (GPS), modified GPS (mGPS), and C-reactive protein/albumin (CRP/Alb) ratio, have prognostic values in many types of cancer." (PMID 33317455, 2020). "CRP indicates the degree of inflammatory reactions in cancer patients and is anestablished prognostic factor." (PMID 35111532, 2020). "Overall and cancer specific survival according to CRP and MMR status, stratified by infiltration of FOXP3+ cells, are illustrated in Kaplan–Meier curves." (PMID 32316975, 2020). "This score, based on the values of preoperative CRP and albumin, was found to have a high prognostic value in many cancer conditions." (PMID 33096884, 2020).
cancer (continued). "Of these, the pretreatment mGPS, a score combining CRP and serum albumin levels, better predicts cancer survival compared with the peripheral blood cell count-based prognostic scores (e.g., NLR and PLR)." (PMID 32587804, 2020). "A descriptive study on dogs with various diseases included a high proportion of patients with immune-mediated diseases or cancer among dogs with > 100 mg/l CRP which is in accordance with our results." (PMID 32434519, 2020). "The systemic inflammatory response, which is usually measured by surrogate blood-based parameters, such as C-reactive protein, neutrophil or platelet count, has been shown to independently predict the clinical outcome of various human cancer types." (PMID 32182693, 2020). "Third, there is evidence that cancer cells increase the production of inflammatory proteins such as CRP." (PMID 33059654, 2020). "Cancer patients often exhibit high levels of CRP in plasma, however there is limited evidence that it accumulates in the tumor microenvironment." (PMID 33235296, 2020). "Different systemic inflammatory indicators including NLR, LMR, CRP, and Alb have been analyzed in several malignant tumors with poor outcome and low therapeutic response." (PMID 33101044, 2020). "However, it remains unclear whether apo levels affect the associations between CRP and cancer." (PMID 31936330, 2020). "Their moderate positive correlation with inflammation markers (CRP, IL-8, IL-6) sustains their role in cancer progression." (PMID 33375435, 2020). "Since CRP is one of the acute phase proteins derived from hepatocytes stimulated by circulating interleukin 6 (IL-6), CRP levels in cancer patients reflect the amount of IL-6 in the circulating blood produced by T-cells or macrophages." (PMID 32567660, 2020). "The inflammation-based Glasgow Prognostic Score (GPS) makes use of the changes in albumin and hypersensitive C-reactive protein (H-CRP) to concisely evaluate the prognosis of cancer patients." (PMID 32355581, 2020). "Patients with advanced stages of cancer exhibit greater tumor load and are accompanied by considerably higher CRP levels than those with early-stage disease." (PMID 31936329, 2020). "This proposed utility of CRP levels to estimate cancer progression are in line with what has been described in assessing disease severity in a number of inflammatory diseases, including analysis of the recent SARS-CoV-2 viral infection (COVID-19)." (PMID 33324413, 2020). "The Glasgow Prognostic Score (GPS), which is based on serum albumin and C-reactive protein (CRP) levels, represents one of the most commonly investigated scoring systems usable for several types of cancer." (PMID 31936329, 2020). "The GPS and mGPS are a combination of CRP and albumin scores, representing methods designed to predict the prognosis of cancer patients." (PMID 32974174, 2020). "There is rising evidence supporting the prognostic role of the plasma CRP level in different cancer entities, including localized and metastatic CRC." (PMID 33023215, 2020). "Most importantly, the present data regarding the prognostic power of the S100A8/CRP ratio seem to suggest a beneficial role of activated neutrophils for cancer patients." (PMID 32098278, 2020). "Studies have reported that baseline CRP and CRP/Albumin are independent prognostic factors for various cancer patients including NSCLC." (PMID 32181373, 2020). "We found that CRP was a significant predictor of cancer-specific survival in both the uni- and multivariable models but for overall survival in the multivariable model only, after exclusion of irradiated patients." (PMID 32316975, 2020). "This is in accordance with clinical tools such as the Glasgow Prognostic Score, a prognostic indicator for various types of cancers calculated with CRP and albumin values." (PMID 32351914, 2020).